NGF (nerve growth factor)
Diseases named in the same sentence as NGF in open-access papers (continued):
Sharing a sentence is not in itself a finding about the gene and the disease.
breast cancer (continued). "NGF stimulates the expression of SNAIL1, SNAIL2 and TWIST1 in breast cancer cells." (PMID 31812953, 2019). "This study has demonstrated that individual expression of NGF or HO1, and the combined NGF/HO1 expression pattern could be prognostic indicators for breast carcinoma patients." (PMID 24180625, 2013). "After being respectively treated with UTI, TXT and UTI+TXT for 48h, the gene expression of IGF-1R, PDGFA, NGF, NF-κB, and JNK2 in human breast cancer cells decreased significantly compared with the control group (P < 0.05) in the order of UTI+TXT > TXT > UTI > control." (PMID 22217202, 2012). "Interestingly, another neurotrophic factor, nerve growth factor (NGF), also stimulates tumor angiogenesis in vivo in mammary carcinoma via the PI3K-AKT pathway." (PMID 23185544, 2012). "Evidence for cross-talk between NGF or EGF and the estradiol pathways has also been demonstrated, and in this regard, the anti-oestrogenic drug tamoxifen can inhibit proliferation by EGF or NGF on MCF-7 breast cancer cells." (PMID 21241485, 2011). "This expression does not discriminate between breast tumor subtype and NGF mRNA levels are expressed at levels comparable to those seen in the MDA-MB-231 breast cancer cell line." (PMID 24212627, 2011). "In this study, we showed that stimulation of the Brn-3b promoter by NGF is blocked by PD98059, suggesting that the mitogenic effects of NGF in breast cancer cells may result in part from its ability to increase the expression of regulators such as Brn-3b." (PMID 21241485, 2011). "The ability of growth factors such as NGF to increase transcription from the Brn-3b promoter is significant because NGF is known to enhance the growth and drive proliferation of breast cancer cells but not of normal breast epithelial cells." (PMID 21241485, 2011). "Indeed, we showed NGF can increase the secretion of VEGF in both HUVEC and MDA-MB-231 breast cancer cells." (PMID 20569463, 2010). "Additionally, further studies regarding neurotrophic factor blockades have indicated that anti-NGF antibodies can significantly reduce the neurotrophic effect of NGF and thus inhibit nerve fiber growth, which is a crucial component in PNI-positive breast cancers." (PMID 40563551, 2025). "However, it has been shown that cancerous tumors can also secrete neurotrophins, such as prostate and breast cancer, which produce NGF (when it is not found in normal breast epithelial cells), inducing an autocrine loop of activation of the TrkA receptor." (PMID 37576898, 2023). "Moreover, in MDA-MB-231 breast cancer cells, flow cytometric analysis also revealed that NGF increased the plasma membrane level of CD44v3 but not CD44v6." (PMID 35346305, 2022). "The binding of ligand NGF with tropomyosin receptor tyrosine kinases A (TrkA) and the TNF-receptor family member p75NTR (NGFR) activates downstream pathways, such as RAS/MAPK and PI3 kinase, resulting in increased cell proliferation and survival of human breast cancer cells." (PMID 34771423, 2021). "However, we have previously shown that p75NTR is not involved in NGF-stimulated invasion of breast cancer cells." (PMID 25840418, 2015). "However, the correlative role of NGF and HO1 and their prognostic impact in breast carcinoma is unknown." (PMID 24180625, 2013). "Although basal activity was slightly lower than that of the WT promoter, this did not account for the loss of inducibility by NGF and EGF, suggesting that key DNA binding sites present in this region are essential for increasing promoter activity in breast cancer cells." (PMID 21241485, 2011). "Interestingly, NGF increased the secretion of VEGF in both endothelial and breast cancer cells." (PMID 20569463, 2010). "Notably, we previously showed that NGF may enhance RhoA activity in breast cancer cells to promote migration/invasion independent of TrkA phosphorylation." (PMID 35346305, 2022).
breast cancer (continued). "Pathway annotation showed that genes in module 0 are highly enriched in components of the endothelin and Nerve Growth Factor (NGF) pathways, in contrast to breast cancer and GBM, which show no such enrichment." (PMID 20482850, 2010). "Indeed, the TrkA phosphorylation inhibitor K252a did not affect the NGF-mediated activation of HER2, suggesting also targeting these receptors for the inhibition of breast cancer cell proliferation." (PMID 36354700, 2022).
pheochromocytoma (82 papers, 2006 to 2026). "This is complicated by the fact that while activation of a SOS/Shc-Grb2 complex has been associated with in vitro RIT1 activation following either NGF or PCAP stimulation of pheochromocytoma cells, biochemical analysis has yet to identify a bona fide RIT1GEF." (PMID 28607354, 2017). "Furthermore, our previous study reported that neurotrophic growth factors such as nerve growth factor induce neuronal differentiation in rat pheochromocytoma cells through ERK and EGR1 activation, associated with p35/CDK5 activation." (PMID 34207842, 2021). "For example, survival of differentiated rat PC-12 pheochromocytoma cells in culture is dependent upon the presence of nerve growth factor (NGF) and removal of NGF from the medium causes an increase in the activities of p38 MAPK and JNK which is necessary and sufficient to induce apoptosis." (PMID 21365009, 2011). "Thus, induction of differentiation in a pheochromocytoma tumor cell line by nerve growth factor (NGF) was associated with a complete growth arrest and development of a sympathetic neuron-like phenotype by extension of neuritic processes similar to NGF-differentiated chromaffin cells." (PMID 28148265, 2017). "PC12 cells, derived from rat pheochromocytoma, differentiate into neuron-like cells in response to nerve growth factor (NGF), activating TrkA-mediated survival signaling pathways." (PMID 41599368, 2026). "The PC12 cells originate from rat pheochromocytoma and differentiate into neuronal phenotypes under the stimulation of nerve growth factor." (PMID 40630924, 2025). "The cell differentiation response of pheochromocytoma cells to different frequencies of pseudo-sinusoidal modulated EGF or NGF concentrations was examined for the first time in this paper." (PMID 40508091, 2025). "To integrate the inside-out and outside-in approaches, we used a microfluidic system to deliver periodic pseudo-sinusoidal pulses of EGF or NGF to pheochromocytoma cells and measured cell differentiation as a function of input frequency (outside-in approach)." (PMID 40508091, 2025). "We first tested the GAP-43 phosphomutants in PC12 cells, a rat pheochromocytoma cell line capable of differentiating into neuronal-like cells upon exposure to soluble Nerve Growth Factor or transfection with neuronal growth proteins such as GAP-43." (PMID 40259946, 2025). "Sievers and colleagues developed injectable Starpeg-Heparin Cryogels encapsulating NGF and rat pheochromocytoma (PC-12) cells to examine the impact of varying concentrations of NGF on PC-12 neuronal differentiation in vitro." (PMID 40458695, 2025). "VGF is a neuroendocrine factor, which was first discovered in a pheochromocytoma cell line when exposed to nerve growth factor (NGF)." (PMID 37624511, 2023). "whereas the pheochromocytoma cells, apoptosis and nerve growth-factor were the most often used keywords in the “Mechanism study” cluster." (PMID 37680890, 2023). "It is required for nerve growth factor (NGF)-dependent neurite outgrowth of pheochromocytoma of the rat adrenal medulla (PC12) cells and hippocampal primary neurons." (PMID 36438565, 2022). "The PC12 are chromaffin cells derived from rat pheochromocytoma, which can differentiate into neuron-like cells when stimulated with Nerve Growth Factor (NGF)." (PMID 35163681, 2022). "Neuro-immune cell interactions were also observed in vitro using differentiated PC12, which is a rat pheochromocytoma cell line, along with nerve growth factor (NGF) and J774.1 cells, which is a cultured mouse macrophage cell line." (PMID 36142564, 2022). "The immortalized PC-12 cell line demonstrated to be a classical neuronal cell model derived from rat pheochromocytoma with the ability to acquire the sympathetic neurons features in a differentiation process in the presence of nerve growth factor." (PMID 35884303, 2022).
pheochromocytoma (continued). "Here we use nerve growth factor (NGF) induced PC12 cells which are derived from pheochromocytoma of the rat adrenal to establish a classical PD in vitro model." (PMID 33646533, 2021). "More recently, a study showed that Gracilaria manilaensis induced the proliferation of neurite-bearing cells in the rat pheochromocytoma cell line, which is believed to mimic the neuroactivity of NGF." (PMID 34571842, 2021). "Given the characteristic of exhibiting sympathetic neuron-like phenotypes under the stimulation of the NGF, the PC12 cell line, which is derived from rat pheochromocytoma cells, is widely used as a model to screen small molecules with NGF-mimicking activities." (PMID 34065446, 2021). "Studies on gangliosides extracted from marine invertebrates have demonstrated neuritogenic activities in the rat pheochromocytoma cell line PC-12 in the presence of nerve growth factor (NGF)." (PMID 33003399, 2020). "VGF was originally identified in a pheochromocytoma cell line in response to the addition of the nerve growth factor (NGF)." (PMID 31682594, 2019). "PC12 cells derived from rat pheochromocytoma were cultured and induced by nerve growth factor (NGF) (25 ng/ml) to differentiate to sympathetic neuron-like cells." (PMID 31616252, 2019). "Bioactivity of the secreted NGF was further assessed by exploring its ability to promote neurite outgrowth in pheochromocytoma cells (PC12), and thus conditioned cell culture experiments were carried out." (PMID 31341171, 2019). "PC12 is a rat pheochromocytoma cell line which on exposure to NGF differentiates into sympathetic‐like neurons, exits the cell cycle, extends neurites, and becomes electrically excitable." (PMID 30690892, 2019). "These compounds showed similar neuritogenic activity toward the rat pheochromocytoma cell line, PC-12 cell, in the presence of NGF as other marine-derived gangliosides." (PMID 30135377, 2018). "As previous gangliosides, GP-3 also exhibited neuritogenic activity toward the rat pheochromocytoma PC-12 cells, in the presence of the NGF, displaying, in this case, a lower effect when compared with ganglioside GM-1." (PMID 30135377, 2018). "PC-12 Adh is a rat pheochromocytoma-derived cell-line, which responds to nerve growth factor (NGF) by switching from an immature chromaffin-cell-like phenotype to a sympathetic-neuron-like one." (PMID 30150574, 2018). "PC12 is a cell line derived from a pheochromocytoma of the rat adrenal medulla, and it has been widely used as a model system for nerve growth factor (NGF)-induced neuronal differentiation." (PMID 30557385, 2018). "These compounds showed neuritogenic activity toward the rat pheochromocytoma cell line PC-12 in the presence of a nerve growth factor." (PMID 30135377, 2018). "This compound showed an interesting neuritogenic activity towards the rat pheochromocytoma PC-12 cell line in the presence of nerve growth factor (NGF) and, when compared to ganglioside GM-1 (25.4%), its effect was better (34.0%)." (PMID 30135377, 2018). "To address this aspect, we used the Nerve Growth Factor (NGF)-induced neurite outgrowth assay in the rat pheochromocytoma cell line PC-12, which is an established in vitro model and is often used to study neuronal differentiation and neurotoxicity." (PMID 29899826, 2018). "First, we describe that HJG acts to induce neurite outgrowth in PC12 cells (a rat pheochromocytoma cell line) like nerve growth factor (NGF) in a concentration-dependent manner (3 μg/ml HJG, p < 0.05; 10–500 μg/ml HJG, p < 0.001)." (PMID 29209220, 2017). "Then, it stimulates microtubule polymerization (rat brain and from PC12 cells) and the extension of neuritis in pheochromocytoma cells that are exposed to nerve growth factor (NGF)." (PMID 28894435, 2017). "Rat adrenal pheochromocytoma PC12 cells can be made to differentiate into cells with a neurone-like phenotype by treatment with nerve growth factor (NGF)." (PMID 29279858, 2017).
pheochromocytoma (continued). "The aim of this study was to investigate the potential of 6-shogaol to mimic the neuritogenic activity of nerve growth factor (NGF) in rat pheochromocytoma (PC-12) cells." (PMID 28646880, 2017). "Oxaliplatin was previously reported to inhibit NGF-stimulated neurite outgrowth in PC12 rat pheochromocytoma cells." (PMID 27782842, 2016). "Next, we tested the bio-functionality of NGF in a rat pheochromocytoma cell line (PC12) and the bio-functionality of GDNF in an organotypic spinal cord culture." (PMID 26388717, 2015). "In laboratory conditions, pheochromocytoma cells undergo differentiation to neural cells upon treatment with nerve growth factor (NGF)." (PMID 25821818, 2015). "Our previous study showed that the ligand of TAM receptors, Gas6, protected the PC12 cells (derived from a pheochromocytoma of the rat adrenal medulla) from the serum- and NGF-deprivation induced apoptosis." (PMID 25514676, 2014). "The model consisted of pheochromocytoma cells grown in tissue culture stimulated with nerve growth factor." (PMID 24410751, 2014). "The PC12 cell line is derived from rat pheochromocytoma, responds to NGF by sprouting axon-like neurites, and has been used extensively to study neuronal differentiation." (PMID 25196344, 2014). "Regarding neural cell differentiation, miR-221 has been found highly up-regulated upon nerve growth factor-induced neuronal-like differentiation of PC12 rat pheochromocytoma cells." (PMID 24155920, 2013). "Here, we investigate its involvement in the nerve growth factor (NGF)-induced differentiation of rat pheochromocytoma (PC12) cells." (PMID 23717400, 2013). "PC12 cells, a cell line derived from a pheochromocytoma of rat adrenal medulla, have been widely used as a model system for nerve growth factor (NGF)-induced neuronal differentiation." (PMID 22655093, 2012). "We examined the effects of hyaluronic acid gel on neuronal differentiation of PC12 pheochromocytoma cells, which respond to nerve growth factor (NGF) by extending neurites and exhibit a variety of properties of adrenal medullary chromaffin cells." (PMID 22174717, 2012). "In pheochromocytoma (PC 12) cells and NGF differentiated-PC 12 cells, ketamine decreased the cell viability while increasing dopamine (DA) concentrations in a dose-related manner." (PMID 22937133, 2012). "PC12 cells, originally derived from a transplantable rat pheochromocytoma, are accepted as a model system for primary neuronal cells because of their ability to respond to nerve growth factor." (PMID 22146536, 2011). "PC12 cells are a cell line derived from a rat pheochromocytoma of the adrenal medulla that extend neurites and undergo growth arrest in the G1 phase of the cell cycle when treated with nerve growth factor (NGF)." (PMID 21464894, 2011). "PC12 cells originating from rat pheochromocytoma upon Nerve Growth Factor (NGF) treatment, switch their phenotype from a proliferating, undifferentiated cell to a post-mitotic, differentiated, neurite-bearing NGF-dependent neuron." (PMID 22028798, 2011). "PC12 is a cell line derived from a pheochromocytoma of the rat adrenal gland and secretes neurotrophins such as nerve growth factor (NGF) and brain-derived neurotrophic factor (BDNF)." (PMID 20625543, 2010). "Indeed, P12 cells represent a cell line derived from a pheochromocytoma of the rat adrenal medulla that has long been used as a model system for NGF-induced outgrowth." (PMID 40141736, 2025). "The isolated compounds were assessedfor their neurotrophic activity in rat pheochromocytoma cells (PC-12)to promote neurite outgrowth on 5 ng NGF supplementation; all thecompounds increased neurite outgrowths, with compounds 3, 4, and 8 exhibiting the strongest effects." (PMID 37440475, 2023). "PC12 cells are produced from a pheochromocytoma cell line derived from the rat adrenal medulla, are readily cultured, and can be differentiated to display neuron-like behaviour by the addition of NGF." (PMID 37373106, 2023).